ABI1 (abl interactor 1)
Diseases named in the same sentence as ABI1 in open-access papers (continued):
Sharing a sentence is not in itself a finding about the gene and the disease.
prostate tumors (3 papers, 2019 to 2024). "Dysregulated ABI1 in prostate tumors is linked to abnormal cell adhesion leading to prostatic intraepithelial neoplasia, characterized by increased AKT activation and decreased levels of E-cadherin, β-catenin, and WAVE2." (PMID 39354505, 2024). "In prostate tumors, loss of ABI1 is correlated with loss of heterozygosity (LOH) at markers of the long arm of chromosome 10." (PMID 39354505, 2024). "Examination of tumor tissue indicated low ABI1 expression in in patients with high-grade prostate tumors and an association between low ABI1 and clinically significant events (biochemical recurrence, metastasis, and death)." (PMID 31530281, 2019). "Our previous studies implicated ABI1 downregulation in high-risk prostate tumors, but the mechanism underlying Abi1 tumor suppressor activity is unclear." (PMID 31530281, 2019). "Downregulation of ABI1 is associated with the high-grade of prostate tumors and is evident in metastatic prostate cell lines." (PMID 31530281, 2019). "ABI1 expression and its association with prostate tumor grade was evaluated in a TMA cohort of 505 patients and metastatic cell lines." (PMID 31530281, 2019). "Although ABI1 gene loss has previously been associated with highly aggressive metastatic prostate tumors, the mechanism by which inactivation of ABI1 promotes invasion remained unclear." (PMID 31530281, 2019). "We investigated the mechanism for ABI1 loss in prostate tumor progression." (PMID 31530281, 2019). "Moreover, ABI1 expression was significantly decreased in Gleason pattern 5 vs. pattern 4 (p = 0.0025) and 3 (p = 0.0012), indicating an association between low ABI1 expression and highly invasive prostate tumors." (PMID 31530281, 2019). "Hence, the most aggressive prostate tumors are associated with low ABI1 expression." (PMID 31530281, 2019). "ABI1 controls prostate tumor progression and epithelial plasticity through regulation of EMT-WNT pathway." (PMID 31530281, 2019). "Analysis of metastatic prostate tumor cell lines and a prostate tumor tissue microarray indicated that low Abi1 expression preferentially affects high-grade prostate tumors." (PMID 31530281, 2019). "Here, we investigated ABI1 downregulation as a mechanism by which prostate tumors gain invasive and metastatic potential." (PMID 31530281, 2019). "Here, we analyzed ABI1 expression in prostate tumor cell lines and patient-derived prostate tumor organoid cell lines (PCa1, 2 and 3)." (PMID 31530281, 2019). "Here we discovered that ABI1 inhibits EMT through suppressing FYN-STAT3 activation downstream from non-canonical WNT signaling thus providing a novel mechanism of prostate tumor suppression." (PMID 31530281, 2019). "Two prostate tumor cell lines carrying ABI1 exon skipping mutations resulting in SH3 domain loss and consequential attenuation of ABL1 binding to ABI1 show loss of negative regulation of ABL1 by ABI1, resulting in increased ABL1 activation." (PMID 39354505, 2024). "Disruption of Abi1 expression in the mouse leads to prostatic intraepithelial neoplasia (PIN) with high penetrance in all lobes, and loss of Abi1 is associated with downregulation of E-cadherin, which together with the PIN phenotype suggests a role of Abi1 in prostate tumor initiation." (PMID 31530281, 2019). "The mechanism of ABI1 isoform dysregulation is unknown, but the evidence of widespread downregulation of ABI1 in high-grade prostate tumors (PCa-1 and 2 cell lines) warrants further inquiries." (PMID 31530281, 2019). "However, the impact of ABI1 loss on integrin expression in the prostate epithelium or in prostate tumors is not known." (PMID 31530281, 2019).
diffuse large B-cell lymphoma (2 papers, 2020 to 2024). "Additionally, a study of mutation and copy number alteration in 20 paired relapsing and non-relapsing diffuse large B-cell lymphomas (DLBCL) found that a gain of ABI1 is associated with relapsing DLBCL." (PMID 39354505, 2024).
hyperplastic polyp (2 papers, 2012 to 2015). A polyp found mainly in the stomach and colon. "Furthermore, they highlight a possible role for Abi1 as a marker for early KRAS mutation in hyperplastic polyps." (PMID 22808230, 2012). "Taken together, it has to be pointed out that the upregulation of Abi1 that we observed is not restricted to carcinogenesis, but can also be observed in inflammation and in very early lesions that do not necessarily progress to cancer, such as hyperplastic polyps." (PMID 22808230, 2012).
invasive breast carcinoma (2 papers, 2022 to 2024). A carcinoma that infiltrates the breast parenchyma. "Another analysis of 988 patients with invasive breast carcinoma identified ABI1 as a prognostic marker associated with decreased overall and disease-free survival." (PMID 39354505, 2024). "Also, our experimental findings consist of high ABI1 protein expression in human invasive breast carcinoma associated with high risks of tumor recurrence and overall survival." (PMID 34967509, 2022). "For example, a study of 988 patients with invasive breast carcinoma found that ABI1 expression positively correlates with older age at diagnosis, earlier tumor recurrence, and lower survival linked to AKT activation, consistent with the role of ABI1 in PI3K signaling." (PMID 39354505, 2024).
leukemia (2 papers, 2020 to 2021). A malignant (clonal) hematologic disorder, involving hematopoietic stem cells and characterized by the presence of primitive or atypical myeloid or lymphoid cells in the bone marrow and the blood. "Remarkably, the p185Bcr-Abl-transformed cells with Abi1 deficiency lost their ability to develop leukemia in syngeneic mice." (PMID 32276588, 2020). "The reduced ERK and Akt activity in p185Bcr-Abl Abi1 KO cells is consistent with the finding that these cells grow slower in vitro and fail to develop leukemia in vivo." (PMID 32276588, 2020). "Together, this study highlights an essential role of Abi1 in Bcr-Abl-induced leukemogenesis and provides a model system for dissecting the Abi1 signaling in Bcr-Abl-positive leukemia." (PMID 32276588, 2020). "Remarkably, we found that complete depletion of Abi1 abolishes the leukemic potential of p185Bcr-Abl cells and the mice implanted with these cells are leukemia free for over 6 months." (PMID 32276588, 2020). "Taken together, our data suggests that Abi1 is also essential for leukemia development in imatinib-tolerant p185Bcr-Abl cells." (PMID 32276588, 2020). "This is in contrast with present studies which show that the complete depletion of Abi1 not only abrogates leukemia development in vivo but also reduces IL3-independent growth in vitro." (PMID 32276588, 2020). "Specifically, despite the prolonged latency, the mice receiving p185Bcr-Abl cells in which Abi1 expression had been knocked down eventually developed leukemia and became moribund approximately 5-week post-injection." (PMID 32276588, 2020). "To determine the role of Abi1 in p185Bcr-Abl-positive leukemia development, we set to completely deplete its expression in p185Bcr-Abl-positive leukemic cells using CRISPR/Cas9-mediated gene editing." (PMID 32276588, 2020). "Our data suggests that the Abi1 pathway is essential for p185Bcr-Abl-induced leukemia development regardless whether these cells develop imatinib resistance or not." (PMID 32276588, 2020). "Despite the importance of Abi1 in intracellular signaling, its role in cancer and leukemia development remains unclear." (PMID 32276588, 2020). "It is possible that the role of Abi1 in Bcr-Abl-induced leukemia development may vary among different hematopoietic cell lineages." (PMID 32276588, 2020). "Moreover, the inhibition of Bcr-Abl-induced leukemia by Abi1 deficiency is independent of the sensitivity of these cells to imatinib, as the imatinib-tolerant p185Bcr-Abl cells also require Abi1 for development of leukemia in vivo." (PMID 32276588, 2020). "The leukemia development in these mice is likely due to the selective expansion of those p185Bcr-Abl cells in which Abi1 has not been knocked down, as suggested by the analyses of both the Abi1 expression in p185Bcr-Abl cells recovered from leukemic mice and the competitive in vivo expansion assay." (PMID 32276588, 2020).
acute myeloid leukemia (1 paper, 2026). Acute myeloid leukemia (AML) is a group of neoplasms arising from precursor cells committed to the myeloid cell-line differentiation. "In contrast, other studies identified human Abi1 as a recurrent fusion partner of mixed-lineage leukemia, frequently disrupted by chromosomal translocation in acute myeloid leukemia." (PMID 41474627, 2026).
atherosclerosis (1 paper, 2021). A disease characterized by the build-up of fatty material and calcium deposition in the arterial wall resulting in partial or complete occlusion of the arterial lumen. "The expression of MBNL1 and Abelson interactor 1 (Abi1) splice variants (Abi1‐e10 and Abi1‐Δe10) was compared between artery tissues from healthy donors and atherosclerosis patients." (PMID 33759281, 2021). "Loss of MBNL1 significantly induces the Abi1‐Δe10 isoform expression by alternative splicing in the macrophage‐like VSMC (VSMC‐M) in artery wall from atherosclerosis patients." (PMID 33759281, 2021).
breast tumors (1 paper, 2022). "While implicated in breast tumor progression, the role of ABI1 in normal mammary tissue remains unknown." (PMID 34967509, 2022). "Thus, our findings strongly suggest that ABI1 is critical for pulmonary metastasis of aggressive breast tumors due to its essential role in sustaining WAVE complex dynamics." (PMID 34967509, 2022). "Indeed, the analysis revealed that invasive breast tumors have higher ABI1 protein expression than poorly invasive tumor samples and that increased ABI1 protein levels are significantly correlated with earlier recurrence and shortened survival." (PMID 34967509, 2022).
colonic carcinoma (1 paper, 2012). "Taken together, these results show an increase in MAPK/PI3K signaling and an overexpression of Abi1 upon transfection of wild-type HDC-9 colonic carcinoma cells with constitutively active KRAS G12D." (PMID 22808230, 2012).
colorectal adenocarcinoma (1 paper, 2012). The most common type of colorectal carcinoma. "In this study, we firstly analyzed the expression and distribution of Abi1, a protein described as an important regulator of actin dynamics, in healthy and inflamed colonic mucosa and precursor lesions as well as colorectal adenocarcinoma and metastasis." (PMID 22808230, 2012).
colorectal tumour (1 paper, 2014). "In that database, 86% of gastric and colorectal tumour specimens showed moderate to strong Abi1 staining intensity with the identical antibody that was used in the present study." (PMID 24913355, 2014).
dementia (1 paper, 2023). Loss of intellectual abilities interfering with an individual's social and occupational functions. "Of these significantly positively correlated autoantibodies, five were differentially expressed in dementia and included CL1A, CBFA2T3, PKLR, APPL1, and NUDT2, whilst two were dysregulated in MCI including ABI1 and NUDT2." (PMID 38107644, 2023).
glioma (1 paper, 2015). A benign or malignant brain and spinal cord tumor that arises from glial cells (astrocytes, oligodendrocytes, ependymal cells). "We next investigated the association of EGFR, Crk, Crk pY251 and Abi1-Iso2 protein expression in the tumor tissues with clinical and pathologic characteristics of glioma patients as previously indicated." (PMID 26473374, 2015). "Inversely, Abi1-Iso2 expression was downregulated in undifferentiated (G4) GBM cancer tissues as compared to lower grade G2 and G3 glioma cancer tissues." (PMID 26473374, 2015).
HCMV infection (1 paper, 2014). "The interaction with WAVE2, ABI1, ABI2, NAP1, CYFIP1, and talin-1 were validated in conventional immunoprecipitation experiments when pUL135 was expressed in both isolation and the context of HCMV infection." (PMID 25121749, 2014).
hyperplastic (1 paper, 2012). "This would also explain the strong upregulation that could be detected among hyperplastic polyps upon KRAS mutation, since these non-adenomatous lesions lack a “background” of Abi1 expression." (PMID 22808230, 2012).
invasive carcinoma (1 paper, 2012). A carcinoma that is not confined to the epithelium, and has spread to the surrounding stroma. "With regard to BRAF and KRAS mutation status in colonic precursor lesions and invasive carcinomas, wefound that KRAS-mutated HPP showed significantly higher Abi1 expression compared to healthy and inflamed mucosa as well as wild-type and BRAF-mutated HPP." (PMID 22808230, 2012). "So, in all precursor lesions and invasive carcinomas, activating KRAS mutations led to a significant Abi1 overexpression against the background of the already existing upregulation in consequence of adenomatous change, perhaps related to enhanced PI3K/Akt signalling in these lesions." (PMID 22808230, 2012).
lymph node metastasis (1 paper, 2021). "In this study, we identified for the first time that elevated expression of ABI1-TSV-11 was related to LsCC lymph node metastasis and shorter OS, and it functions as an independent risk factor of poor prognosis in LsCC." (PMID 34031495, 2021). "We found a key ABI1-TSV, ABI1-TSV-11, that associates with lymph node metastasis and short overall survival (OS) and thus serves as an independent risk factor for LsCC." (PMID 34031495, 2021). "Here, we firstly identified ABI1-TSV-11 as a key TSV affecting the metastasis and prognosis of left-sided colorectal cancer (LsCC) and its elevated expression is related to lymph node metastasis and shorter overall survival (OS) in LsCC by analyzing data from The Cancer Genome Atlas and TSVdb." (PMID 34031495, 2021).
pancreatic cancer (1 paper, 2023). "Our studies link RBFOX2-associated alternative splicing of ABI1 to pancreatic cancer progression." (PMID 38114498, 2023). "Utilizing ex vivo and in vivo approaches, we defined a network of RBFOX2-controlled alternative splicing events linked to cytoskeletal remodeling and specifically associated exon-skipping in ABI1 with enhanced migratory potential and enrichment at the cell periphery of pancreatic cancer cells." (PMID 38114498, 2023). "To further investigate the biological role of RBFOX2-mediated ABI1 exon 9 skipping to promote pancreatic cancer progression, we induced ABI1 splice-switching in Panc1 cells using an ABI1 AON to mimic the ABI1 ∆PSI observed with RBFOX2 knockdown." (PMID 38114498, 2023). "RBFOX2 mediated splicing of ABI1, encoding the Abelson-interactor 1 adapter protein, controls the abundance and localization of ABI1 protein isoforms in pancreatic cancer cells and promotes the relocalization of ABI1 from the cytoplasm to the periphery of migrating cells." (PMID 38114498, 2023).
papillary thyroid carcinoma (1 paper, 2015). "Interestingly, Abi1 is one of the predicted targets of miR-1991-3p, which induces macropinocytotic vacuoles and causes non-apoptotic death in papillary thyroid carcinoma cells." (PMID 25762935, 2015).
Pleural effusion (1 paper, 2022). The presence of an excessive amount of fluid in the pleural cavity. "For comparison with other body fluids (i.e., plasma/serum, BAL, and pleural effusion), 153 out of 912 MV proteins were pleural effusion-specific proteins, including ABI1, BSG, CAV1, GRB2, RAS proteins, and SRC." (PMID 35158999, 2022).
prostate (1 paper, 2019). "Isoform splice aberrations may not be related to simple splicing events or somatic mutation events; hence, the mechanism by which ABI1 downregulation contributes to prostate tumorigenesis may extend beyond the overall protein level downregulation." (PMID 31530281, 2019).
Salmonella Infections (1 paper, 2024). Infections with bacteria of the genus SALMONELLA. "Additionally, enhanced ABI1 phosphorylation by ABL1 is observed in response to Salmonella infection." (PMID 39354505, 2024).
cancer (25 papers, 2012 to 2025). A tumor composed of atypical neoplastic, often pleomorphic cells that invade other tissues. "Altogether, ABI1 overexpression in cancer is associated with a mesenchymal phenotype, characterized by increased migration and matrix dissolution, promoting invasion and metastasis of tumor cells." (PMID 39354505, 2024). "ABI1 expression level in cancer patients is also associated with differences in 5-year survival, and in some cancers associated with cancer stage." (PMID 39354505, 2024). "As such, ABI1 dysregulation is both directly and indirectly associated with disease, including pathogen infection and cancer." (PMID 39354505, 2024). "In these cancers, ABI1 expression is also positively correlated with KRAS mutation and is proposed to be an early marker for KRAS mutagenesis in hyperplastic polyps." (PMID 39354505, 2024). "Dysregulation of Abelson interactor 1 (ABI1) is associated with various states of disease including developmental defects, pathogen infections, and cancer." (PMID 39354505, 2024). "We used proximity‐dependent labeling to detail mechanistic links between ABI1 and SFKs, STAT3, and NF‐κB and uncover details of involvement of ABI1 in cancer‐linked signaling pathways." (PMID 36635880, 2023). "Alterations in ABI1 expression have been associated with tumor initiation and progression in human cancers, thus indicating that ABI1 protein levels must be tightly regulated in cells." (PMID 34967509, 2022). "Pathogenic roles of ABL1 are further discussed in the ABI1 in cancer section of this review." (PMID 39354505, 2024). "Furthermore, while ABI1 point mutations, copy number variations, and even oncogenic fusion proteins are observed in cancer patients, they are rare." (PMID 39354505, 2024). "Both elevated and decreased levels of ABI1 are associated with different types of cancer." (PMID 36635880, 2023). "We start with a description of mechanisms by which ABI1 regulates the actin cytoskeleton, followed by a review of the roles ABI1 plays in development, pathogen infection, smooth muscle contraction, and cancer." (PMID 39354505, 2024). "High ABI1 expression is correlated with shorter survival, increased cell invasiveness, more advanced-stage and higher-grade tumor, increased cancer antigen level, and suboptimal surgical debulking." (PMID 39354505, 2024). "In different cancers, ABI1 promotes a mesenchymal-like phenotype and metastasis through RAC1 activation via the ABI1/SOS1/EPS8 complex." (PMID 39354505, 2024). "ABI1 plays a complex role in cancer signaling, and both downregulation and upregulation are observed across cancer types." (PMID 39354505, 2024). "This section reviews molecular mechanisms by which overabundance of ABI1 promotes cancer cell motility and invasion in different types of cancer." (PMID 39354505, 2024). "ABI1 is frequently reported to act as a tumor suppressor, as indicated by lower ABI1 expression observed in some types of cancer cells." (PMID 39354505, 2024). "Links among protein signal transduction processes, mediated by adaptor proteins such as ABI1, provide a pharmacologically relevant level of detail necessary to deconvolute cancer cell development and persistence." (PMID 39354505, 2024). "In the following sections, the mechanistic roles ABI1 plays in cancer signaling are discussed to highlight both reported divergent and convergent activities of ABI1." (PMID 39354505, 2024). "We measured the proximal interactome of an adaptor protein frequently downregulated in cancer—Abelson Interactor 1 (ABI1)—using proximity‐dependent biotin labeling by TurboID followed by mass spectrometry." (PMID 36635880, 2023). "To interrogate the role of ABI1 in cancer development, we mapped the ABI1 interactome using proximity‐dependent labeling (PDL) with biotin followed by mass spectrometry." (PMID 36635880, 2023).